IL1B (interleukin 1 beta)
Diseases named in the same sentence as IL1B in open-access papers (continued):
Sharing a sentence is not in itself a finding about the gene and the disease.
liver inflammation (continued). "AP-1, TLR2, and IL1-β, genes that are differentially regulated during the pathological progression of NASH liver inflammation, and SCD1, LEPR, and other genes related to NASH lipid deposition, were regulated by caffeine, but EGCG had no significant regulatory effect." (PMID 34881283, 2021). "In addition, a strong correlation is demonstrated between levels of IL-1β and severity of liver inflammation in HBV patients, implying that NLRP3-mediated IL-1β is the potential driving force of HBV-induced viral hepatitis." (PMID 30319645, 2018). "However, the levels of TNF-α (P < 0.05), IL-1β (P < 0.01), and particularly IFN-γ (6.55-fold increase, P < 0.01) were significantly increased in the serum of mice with hepatitis." (PMID 29695839, 2018). "In addition, IL-2, IL-6, IL-1β and TNF-α were maximally expressed at 6h, indicating these four cytokines mainly expressed in the early phase of Con A-induced hepatitis." (PMID 24498418, 2014). "The mRNA expression of IL-1β was not greatly increased following L2-MHV3 hepatitis compared to control mice." (PMID 24058536, 2013). "IL-6 has been shown to have a suppressive effect on TNFα and IL-1β production in peripheral blood mononuclear cells and exerts its anti-inflammatory effects in hepatitis by reducing the production of TNF." (PMID 19014513, 2008). "Moreover, XZTZ pretreatment notably decreased the high levels of pro-inflammatory cytokines induced by alcohol in the liver, including TNFA, IL-6, IL-1B, and MCP-1, indicating that XZTZ could ameliorate alcohol-induced liver inflammation." (PMID 38681193, 2024). "In addition, in one mouse model of MASLD, SB reduced hepatitis activity according to the NAS scale, production in the liver of TNF-α, IL-1β, interferon-γ, and IL-10 as well as the inflammatory cell chemoattractant CCL-2 and macrophage (Kupffer cells) biomarker F4/80." (PMID 39203520, 2024). "The gradient changes in IL-1β, TNF-α, NF-κB, cAMP, PKA, CREB, and CYP2D6 during the inflammatory process, along with the occurrence and remission of inflammation, suggest that IL-1β may be involved in the pathological process of hepatitis." (PMID 37833431, 2023). "Among these cytokines, TNF-α and IL-1β could be the critical mediators for development of ConA-induced hepatitis, since TNF-α-deficient mice and NLRP3- and caspase-1-deficient mice that do not produce IL-1β are almost protected from ConA-mediated liver damage." (PMID 33809904, 2021). "Similarly, increased IL-1α levels in AVH-E vs recovery in the current series of patients and increased levels of IL-1β and TNF-α in AVH-E and recovered cases in our previous report suggest their probable role in the pathogenesis of hepatitis and hepatocytic injury." (PMID 22384080, 2012). "However, the concentrations of plasma IL-6 and IL-1β in ASC were not different from those of HBV infected individuals with hepatitis (CHB &AHB)." (PMID 21639870, 2011). "Furthermore, recombinant human IL-1 receptor antagonists (rHIL-1RAs) alleviate liver inflammation and reduce NLRP3, caspase-1, and IL-1β production in hepatocytes by scavenging ROS and inhibiting pyroptosis, suggesting that the NLRP3 inflammasome may be a potential therapeutic target for AIH." (PMID 39917567, 2025). "Moreover, we found that elevated levels of inflammatory cytokines (TNF-α and IL-1β) were positively correlated with serum enzymes (ALP, ALT, and AST) in IC group, which is further demonstrating the applicability of these enzymes in monitoring the liver inflammation." (PMID 30483393, 2018). "We confirmed a significant decrease in iNOS, COX2, IL-6, IL-1β, and TNF-α in AGF geese, and we found them to be involved in ileal permeability and ileal and liver inflammation in geese lacking pasture supplementation." (PMID 38003191, 2023).
migraine (119 papers, 2009 to 2026). "A study on single nucleotide polymorphisms identified the IL1B -3953\u00B0C/T variant as a potential biomarker for migraine susceptibility." (PMID 41404467, 2025). "In a recent meta-analysis, IL-6, IL-8, IL-1β, and tumor necrosis factor α were the proinflammatory cytokines implicated in migraine patients." (PMID 38369488, 2024). "In terms of migraine-related disability, an association between IL1B expression and the Migraine Disability Assessment was found in hormonal migraineurs, regardless of menstrual phase." (PMID 38338971, 2024). "First, proinflammatory cytokines, such as interleukin (IL)-1b, IL-6, IL-8, and tumor necrosis factor-α, have been implicated in migraine pain and are increased during migraine attack, which play a critical role in the pathogenesis of IBD30." (PMID 38212517, 2024). "SD as the electrophysiologic event underlying migraine attacks has been demonstrated to further temporarily upregulate pro-inflammatory cytokines such as IL-6, IL-1β and TNF-α during migraine attacks." (PMID 37596546, 2023). "Cytokines and especially IL-1β have been linked to migraine and cluster headache and an involvement of pro-inflammatory cytokines in the pathophysiology of primary headaches is probable." (PMID 26931452, 2016). "Pro-inflammatory cytokines like Interleukin-1 beta (IL-1β) have been implicated in the pathophysiology of migraine and inflammatory pain." (PMID 21394197, 2011). "Imbalances in the gut microbiota abundance may affect the release of neurotransmitters and inflammatory mediators, such as glutamate, calcitonin gene-related peptide, and interleukin (IL)-1β, which might increase the risk of migraine." (PMID 38690367, 2024). "Results obtained from animal models of headache also support that immunological responses associated with cytokines are involved in the mechanism of migraine, including enhanced production of several inflammatory cytokines, such as IL-1β, IL-6, and TNF-α during CSD." (PMID 37287623, 2023). "It has been reported that proinflammatory factors, such as TNF-α and IL-1β, may be associated with the release of neuro-mediators of pain in the migraine initiation." (PMID 37460956, 2023). "Non-steroidal anti-inflammatory drugs (NSAIDs) have long been used in treating migraine attacks, so that multiple cytokines, such as IL-1β, tumor necrosis factor (TNF), and IL-6, have been associated with the pathogenesis of migraine, as their levels are altered in migraine patients." (PMID 36247795, 2022). "In recently published studies, excessive serum levels of IL1B (proinflammatory cytokine) in patients suffering from migraines revealed that migraines had a tightened association with inflammation occurring within the peripheral endings of sensory neurons in the trigeminal ganglion system." (PMID 36079577, 2022). "In addition, we examined several other molecules putatively involved in migraine pathophysiology: SP, IL-1β, IL-6 and TNF-α which have all been shown to be associated with activation of the trigeminovascular system." (PMID 28337634, 2017). "Plasma cytokine levels have been studied previously in primary headache disorders, with higher levels of pro-inflammatory cytokines IL-6, IL-8, TNF-⍺, and IL-1β reported in migraine compared to healthy controls." (PMID 40991059, 2025). "Previous reports, demonstrated acute NTG-induced mast cell inflammation and increases in proinflammatory cytokines like TNF-α and IL-1β in the colon, providing critical groundwork for GI involvement in migraine." (PMID 41226532, 2025). "Consistent with Il1b emerging as a shared hub, a prior study using a familial hemiplegic migraine model reports IL1RN upregulation after cortical spreading depression." (PMID 41465107, 2025). "Pro-inflammatory cytokines such as IL-1β, IL-6, IL-8, and TNF-α are implicated in both migraines and GIDs, contributing to visceral pain and systemic inflammation." (PMID 39861467, 2025).
migraine (continued). "It should be noted that aSMase activity can be increased by the action of pro-inflammatory stimuli, such as Tumor Necrosis Factor α (TNF-α), Interleukin-1β (IL-1β) or cytosolic phospholipase A2 (cPLA2), also involved in migraine." (PMID 40002346, 2025). "In animal models, nitroglycerin-induced migraine correlates with elevated IL-1β and IL-6 levels, indicating delayed meningeal inflammation." (PMID 40426647, 2025). "Compared with the control group, the blood levels of IL-1β and IL-10 were increased in migraine patients." (PMID 39416954, 2024). "Further, the central sensitization, which is an important mechanism for the emergence of chronic migraine, can also be influenced by the activation of the inflammasome mediating the release of IL-1β in a migraine-model." (PMID 38431578, 2024). "Factors such as interleukin (IL)-1β, nuclear factor kappa-B(NF-κB), prostaglandin E2 (PGE2), and nitric oxide (NO) play roles in migraine associated with activation and sensitization of the trigeminovascular system." (PMID 39159242, 2024). "In the migraine models’ trigeminal ganglion (TG), higher levels of microglial activation and increased production of IL-1β were observed." (PMID 37450927, 2024). "For example, propionate and butyrate reduced the onset of pain in a nitroglycerine-induced mouse model of migraine and reduced the release of IL-1β and TNF-α in the ileum." (PMID 38690367, 2024). "On the other hand, during migraine attacks, there is an increase in the release of pro-inflammatory cytokines such as IL-1β, IL-6, and TNF-α." (PMID 39107712, 2024). "Numerous studies indicate an elevation in pro-inflammatory cytokines, including IL-1β, IL-6, IL-8, and TN-αduring the interictal phase of migraines." (PMID 39015315, 2024). "Previous studies have suggested that inflammatory reactions play a certain role in the occurrence and development of adult migraine or animal models, which are most on the pro-infammatory, such as cytokines IL-1β, IL-6, TNF-α, and CGRP unfolded." (PMID 38356891, 2024). "This corresponds with our finding that IL-1β was the cytokine which was consistently raised during the ictal period of migraine." (PMID 37016284, 2023). "Of the 25 overlapping genes/loci, 6 genes/loci were associated with more than 2 phenotypes in HPGDB (COMT, OPRD1, IL1A, IL1B, TSPAN2/NGF, GDF5), and 15 genes were associated with migraine." (PMID 37144689, 2023). "Not only IL-1β but also TNF-α and IL-6, which are associated with migraine, as pointed out in this review, have already been established for clinical application in rheumatic diseases." (PMID 37176049, 2023). "Peripheral levels of pro-inflammatory cytokines, such as interleukin-1β (IL-1β), IL-6, IL-8, and tumor necrosis factor-α (TNFα) were elevated in patients with migraine." (PMID 37287623, 2023). "A recent in vivo study induced a rat migraine model with dural electric stimulation and found an increase in serum inflammatory factors, including IL-1β, TNF-α and IL-6." (PMID 37190506, 2023). "Studies conducted on animal models have provided a possible link between IR and migraine, considering that several vascular mediators, interleukins or cytokines (TNF-α, C-reactive protein, IL-1β, IL-6, and IL-8), have an important role in both IR and migraine." (PMID 37886939, 2023). "To investigate the effect of inhibiting glycolysis on the release of pro-inflammatory factors in migraine, we used WB to examine the expression of IL-1β and IL-6 in the medulla dorsal horn." (PMID 37090989, 2023). "The proinflammatory cytokines IL-6, TNF-α, and IL-8 are higher in patients with migraine than healthy controls, and IL-1β levels are raised during migraine attacks." (PMID 37016284, 2023). "The activation of microglia and subsequent release of various pro-inflammatory cytokines such as IL-6 and IL-1β lead to hyperalgesia or allodynia in experimental migraine models." (PMID 37090989, 2023).
migraine (continued). "During migraine attacks, pro-inflammatory factors such as interleukin-6 (IL-6) and interleukin-1β (IL-1β) are elevated in the serum of migraineurs." (PMID 37090989, 2023). "Several major cytokines, including IL-1β, IL-6 and tumor necrosis factor (TNF), have been thought to be linked to migraine pathophysiology, as their levels are altered in individuals with migraine." (PMID 35884650, 2022). "On one hand, it was observed that female migraineurs have increased levels of pro-inflammatory cytokines (TNF-α, IL-1β, IL-6, IL-8) during both the migraine attack and the migraine-free period." (PMID 35456034, 2022). "It was reported that several major cytokines, such as TNF-α, IL-1β, and IL-6, were elevated in patients during migraine attacks." (PMID 35928284, 2022). "Neuroinflammation pathways, specifically those involving inflammasome proteins, such as IL-1β, IL-18, and caspase-1, seem promising candidates as biomarkers or treatment targets in migraine, providing some interesting direction for further study." (PMID 35896985, 2022). "One study showed that migraine patients have higher levels of interleukin 1-beta (IL1-β) and interleukin-6 (IL6), and lower levels of interleukin-10 (IL10) compared to healthy control patients." (PMID 35432179, 2022). "Recent studies investigating neuroinflammation in migraine reveal the role of inflammasome via inflammasome complex players including IL-1β and IL-18." (PMID 35896985, 2022). "As histological examination is not feasible in humans, clinical studies examined monocytes in blood taken from the jugular vein during spontaneous migraine attacks instead, finding increased iNOS expression and higher levels of IL-1β and IL-6." (PMID 35650524, 2022). "Clinical and experimental studies investigating neuroinflammation in migraine demonstrated the role of inflammasome only indirectly, that is via inflammasome complex players including IL-1β, IL-18, and caspase-1." (PMID 34112082, 2021). "In patients with migraine, peripheral levels of pro-inflammatory cytokines, such as interleukin-1β (IL-1β) and tumor necrosis factor-α, are known to be increased." (PMID 34445635, 2021). "Of note, we also found that IL-1β levels are higher in a subgroup of patients with migraine, suggesting a pro-inflammatory state in these patients." (PMID 34575163, 2021). "During migraine attacks (ictal period), interleukin-1β (IL-1β), IL-6, IL-8, and tumor necrosis factor-α (TNF-α) are increased." (PMID 34445635, 2021). "In recent studies, high serum levels of IL-1β, IL-6, and TNF (proinflammatory cytokines) in patients with migraine indicated that migraine was associated with inflammation within peripheral endings of trigeminal ganglion sensory neurons." (PMID 33995549, 2021). "The plasma and CSF levels of these mediators (e.g., CGRP, TNFα, and IL-1β) are enhanced during migraine attacks." (PMID 35052756, 2021). "MCC950 was previously shown to be able to reduce CGRP and IL-1β expression in the trigeminal ganglia of a murine migraine model and reduce Iba1 expression in the hippocampus of aged mice with neurocognitive disorders." (PMID 34832855, 2021). "A study based on migraine patients from China demonstrated that they had higher levels of IL-6, IL-1β, and TNF compared to healthy controls." (PMID 33020432, 2020). "Inter-ictal saliva concentrations of oxytocin and IL-1β were significantly higher in migraine patients compared to healthy controls." (PMID 30795781, 2019). "TNFα, PGE2, IL-6, and IL-1β are proinflammatory cytokines which have been demonstrated in the process of migraine." (PMID 31428213, 2019). "Of interest, ictally elevated IL-1β concentrations were observed in the jugular blood of migraine patients." (PMID 30795781, 2019). "A high level of pro-inflammatory cytokines including IL-1β in patients with migraines had been described." (PMID 28196516, 2017). "The pro-inflammatory cytokine IL-1β and other cytokines are elevated in migraine and cluster headache patients." (PMID 26931452, 2016).
migraine (continued). "The observation that IL-1β is elevated in plasma during a migraine attack points to an involvement in migraine pathophysiology." (PMID 21394197, 2011). "Curcumin, a natural NF-κB inhibitor, lowered IL-6 and CRP and IL-1β in these studies, and might thus help “cool off” the chronic inflammatory state in migraine." (PMID 41377228, 2025). "In migraine, activation of the immune-neurological system occurs, resulting in the release of pro-inflammatory cytokines such as tumor necrosis factor-alpha and interleukins, especially interleukin-1 beta and interleukin-6." (PMID 40427393, 2025). "Clinical studies on chemokines and cytokines have yielded mixed results: during migraine attacks, levels of pro-inflammatory mediators such as interleukin-1β (IL-1β), IL-6, and IL-8 increase, while levels of anti-inflammatory mediators both increase (IL-10) and decrease (IL-4 and IL-5)." (PMID 41515906, 2025). "A recent review highlights the therapeutic potential of IL-1β axis modulation in migraine, where IL-1 antagonists like Anakinra may suppress neuroinflammatory cascades to relieve the pain." (PMID 40248013, 2025). "This review of randomized trials highlights that elevated serum cytokines (particularly IL-1β, IL-6, and TNF-α) are associated with increased migraine frequency and may contribute to migraine chronification." (PMID 41377228, 2025). "IL-1β can induce pain hypersensitivity and blood-brain barrier changes; thus, it could feasibly contribute to migraine progression." (PMID 41377228, 2025). "IL-1β, a master regulator of inflammation, has been less studied in CM specifically, but our review highlights a trial where combined therapy lowered IL-1β and improved migraines." (PMID 41377228, 2025). "Likewise, circulating IL-1β, IL-6, or IL-8 levels are often enhanced in migraineurs compared to healthy controls, especially during the ictal stage of migraine, as recently shown by a meta-analysis." (PMID 38397400, 2024). "We have identified higher levels of IL-6, IL-8 and TNF-α in patients with migraine compared to healthy controls, higher levels of TGF-β and TNF-α in tension-type headache compared to healthy controls, and higher levels of IL-1β during attacks of migraine compared to the interictal period." (PMID 37016284, 2023). "Furthermore, adults experiencing aura migraine have significantly elevated plasma levels of IL-1β during periods free from headaches and during the early onset of migraine attacks, in comparison to individuals with migraine that do not present with aura." (PMID 37755358, 2023). "While IL-1β has a well-identified role in migraine pathogenesis, CXCL1 and CCL2 are associated with pain hypersensitivity and more recently with migraine." (PMID 36359895, 2022). "Blocking these pathways using immunologic agents such as CGRP antibody, anti-CGRP receptor antibody, and interleukin-1 beta (IL-1β)/interleukin 1 receptor type 1 (IL-1R1) axis-related agents may be promising as potential prophylactic migraine treatments." (PMID 36247795, 2022). "The aim of this study was to investigate whether functional polymorphisms in the IL-1 family (IL-1α, IL-1β and IL-1RN), IL-6 and TNF-α genes may influence the response to oral NSAID administration or triptans during migraine attacks." (PMID 36614097, 2022). "Moreover, intermediate-dose XZR had a similar beneficial effect, as it reversed the high levels of TNF-α (15.91 ± 6.93 pg/mg protein), IL-1β (38.20 ± 0.76 pg/ml), and IL-6 (17.76 ± 3.02 pg/ml) in rats with migraine (p < 0.05)." (PMID 35928284, 2022). "Similarly, the intestinal damage following NTG-induced migraine was indicated by increased staining of the IL-1β marker across the intestinal layers, compared to the control mice (respectively)." (PMID 34685736, 2021).